NOTCH1 (notch receptor 1)
Diseases named in the same sentence as NOTCH1 in open-access papers (continued):
Sharing a sentence is not in itself a finding about the gene and the disease.
cancer (continued). "In addition, six tumor suppressor genes previously implicated in cancer (BTK, CHD1, FN1, NFATC2, NOTCH1, and NRP1) were found in at least two samples." (PMID 34489456, 2021). "Moreover, simultaneous inhibition of SMAD4 and NOTCH1 led to reduction of EMT activities in cancer cells." (PMID 33430387, 2021). "Notch1 is associated with EMT, metastases, and poor prognosis in different cancers including EC." (PMID 34298609, 2021). "Finally, combined treatment was able to significantly downregulate LGR5 and Notch1 in SW620 cancer stem cell (CSC) colonospheres." (PMID 34959725, 2021). "NOTCH1 was expressed at lower levels when compared to HFK1 in both cancer cell lines." (PMID 34944802, 2021). "While increased NOTCH1 expression is associated with a poor prognosis and/or resistance to treatment in cholangiocarcinoma cancer, ovarian cancer, and ESCC, the role of NOTCH3 in cancer is less well understood." (PMID 34042293, 2021). "With respect to insight into anti‐cancer signaling of CaNV+MB‐Drug, the expression of Notch‐1 downstream factors (cleaved Noth‐1 and HES‐1) significantly increased, while Notch‐1 expression remained unchanged, indicating Notch‐1 pathway as a major mechanism to drive the CaNV+MB‐Drug effect." (PMID 34664430, 2021). "Accumulating literature has reported that oestrogen could up‐regulate NOTCH1 to promote cancer cell proliferation." (PMID 33237585, 2021). "The lack of inambiguous benefit of combining anti-Notch agents with cisplatin in this cancer may be related to the oncosuppressive role of Notch1 signaling." (PMID 34680255, 2021). "The Notch1 pathway controls cancer stem cell proliferation and fate." (PMID 35723384, 2021). "Furthermore, since EMT is a reversible process, it would be feasible to recruit back stem-like cancer cells by inducing a reverse driver switch from Notch1 to mutant EGFR, and thus restoring sensitivity to EGFR TKIs." (PMID 33922104, 2021). "Consequently, cancer-activated astrocytes express Jagged1, which interacts with Notch1 in cancer cells to sustain CSCs in brain metastasis." (PMID 35582386, 2021). "Similarly, the network figures for the remaining networks show similar positioning for many important cancer genes: NOTCH1 in liver, NOTCH3 and EGFR in lung are some other examples." (PMID 34115745, 2021). "For instance, the hub nodes MYC, NOTCH1 and SHH have been associated to different types of cancer." (PMID 33632303, 2021). "The NF1 p.T700I and NOTCH1 p.V2153M neoantigens may represent potential targets for immunotherapy in hypermutated cancer patients." (PMID 34503126, 2021). "Thus, the relationship between the Notch1 pathway and cancer cell autophagy needs further confirmation." (PMID 34495871, 2021). "The majority of oncogenic alterations of NOTCH receptors in human cancers occur in the NOTCH1 gene." (PMID 33407740, 2021). "Among these genes, TP73, GNAS, and NOTCH1 are notable ones with known relations to cancer." (PMID 33711952, 2021). "Likewise, recently it has been demonstrated that Chrysin activated Notch1 signaling pathway, induced apoptosis, and inhibited cancer cell growth in in vitro and in vivo models of anaplastic thyroid carcinoma." (PMID 34680255, 2021). "In conclusion, our study confirmed the oncogenic role of FEZF1-AS1 in NSCLC and we proposed that FEZF1-AS1 may sponge miR-34a to up-regulate NOTCH-1 to promote cancer cell invasion and migration." (PMID 32349744, 2020). "Therefore, it is ofinterest to document the molecular docking analysis of phytocompounds from Andrographis paniculata binding with protein (NOTCH1) in the Notch-signaling pathway in the context of cancer." (PMID 34803268, 2020).
cancer (continued). "Similarly, gene expression changes associated with breast EMT and cancer progression were detected, as the reduction of ERa and ERBB2 and the increase of NOTCH1 and WNT5B." (PMID 32699630, 2020). "The Notch1 is an oncogene factor that its role in different cancers has been evaluated." (PMID 32380783, 2020). "Thus, it is unclear if the associations between NOTCH1 and expression of ALDH3A1 and SOX2 represent a genuine shift toward a cancer stem cell phenotype, or instead signify the transition to early differentiated progenitors (i.e., transiently amplifying cells)." (PMID 33322834, 2020). "In addition, USP18 functions as a deubiquitinase and stabilizes Notch1, which in turn regulates tumorigenesis and cancer progression in a Notch1-dependent manner." (PMID 33051403, 2020). "Our recent data suggest that NOTCH1 controls genes involved in early differentiation that could have different phenotypic consequences depending on the cancer’s genetic background, including acquisition of pseudo-stem cell-like properties." (PMID 33322834, 2020). "While MYC is a “pan-cancer” oncogene, NOTCH1 is more “T-ALL-specific”." (PMID 32380791, 2020). "Interestingly, both trastuzumab sensitive and resistant cancer cell growth was completely inhibited when Notch 1 was knocked down using siRNA." (PMID 32575680, 2020). "Among these, GSI inhibitors are actively considered as cancer therapeutic options, based on the finding that the NOTCH1 signal inhibition in selective tumors might be curative." (PMID 32042099, 2020). "Notch-1 has been shown to regulate motility in cancer cells." (PMID 33411691, 2020). "In summary, we reveal DYRK2 as a novel negative regulator of NOTCH1 levels and activity, which represents a new control mechanism of the expression and function of this transcription factor with potential implications in cancer." (PMID 31605148, 2020). "Many studies revealed that Notch1 signalling is involved in the regulation of cancer." (PMID 33051403, 2020). "Notch1 is a highly conserved member of Notch family and exerts a vital role in various cancers." (PMID 32948241, 2020). "In addition to Noxa up-regulation, MPM cells treated with 25 mM metformin, showed an inhibition of Notch1, a known suppressor of Noxa expression in cancer cells." (PMID 33537296, 2020). "In summary, we reveal a novel mechanism of regulation for NOTCH1 which might help us to better understand its role in cancer biology." (PMID 31605148, 2020). "C-Myc is also an important transcriptional target of Notch1 signaling in various cancers." (PMID 33224949, 2020). "Moreover, we found that DYRK2 modulation by chemotherapeutic agents has a relevant effect on the viability, motility and invasion capacity of cancer cells expressing NOTCH1." (PMID 31605148, 2020). "Moreover, the expression of the EMT mediators Notch1 and Wnt5B is increased, both of which are associated with breast EMT and cancer progression." (PMID 32699630, 2020). "In addition, cancer-associated adipocytes secrete chemokines such as Chemokine (C–C motif) ligand 2 (CCL2), which activates NOTCH1 signaling pathway and induces the stemness of the cancer cells." (PMID 32796516, 2020). "Some miRNAs, such as miR-34a, targets NOTCH-1 to inhibit cancer progression." (PMID 32349744, 2020). "Notch1-driven HCC progression could be reversed by depletion of RNF187, whereas overexpression of RNF187 counteracted the inhibition of cancer progression mediated by Notch1 knockdown." (PMID 31477177, 2019). "Expression of Notch1 is pivotal for early cancer development." (PMID 30917608, 2019). "Here, we show that SAHA individually or in combination with CDDP significantly reduces the expression of Notch1, which might be beneficial for this particular cancer type where clear oncogenic Notch1 signaling has been described." (PMID 31357442, 2019).
cancer (continued). "In this cancer, translocations activating transcriptional regulators such as LMO1/2, TAL1/2 and TLX1/3, together with the acquisition of activating mutations in the NOTCH1 gene, are considered hallmarks of the disease." (PMID 31771951, 2019). "FOXM1 and Notch1 regulate expression of cell cycle and metabolic genes in cancer." (PMID 31208996, 2019). "Moreover, overexpression of RNF187 counteracted the inhibitory effect of Notch1 knockdown on cancer progression." (PMID 31477177, 2019). "Inhibiting Notch1 in an HNSCC xenograft mouse model resulted in reduced cancer stem cell renewal." (PMID 30917608, 2019). "The Notch1 mutant decoy peak could simply be less advanced on the path to cancer or may simply be less likely to evolve toward cancer." (PMID 30848555, 2019). "Notch 1 inactivation has been related to a decrement in the oxygen consumption flux in breast MDA-MB-231 carcinoma: that is, Notch 1 may positively modulate mitochondrial function." (PMID 31600993, 2019). "In addition, the expression level of key proteins found to be over-expressed frequently existed in cancer stem cells, and anti-apoptotic protein Bcl-2, Notch-1 and MMP-9 were detected to increase in different degrees." (PMID 29914196, 2018). "We hypothesized that the Tg6F-mediated increase in Notch1 and Notch 2 with increased Dll4 and Dll1 expression in the jejunum in the cancer model might affect the immune cell repertoire." (PMID 29899427, 2018). "Importantly, MDA-MB-231 LM and matching parental cells expressed nominal levels of NOTCH1 and NOTCH2, suggesting that LY411575-mediated inhibition of cancer cell seeding and metastatic growth was primarily linked to inhibition of the NOTCH3 signaling pathway." (PMID 30180881, 2018). "Even through Notch SNPs were mostly reported in cancer, considering the vital functions of Notch1 in hearing maintenance and repair, we hypothesized that polymorphisms in the Notch1 gene may also be associated with the genetic susceptibility to NIHL." (PMID 30217173, 2018). "We detected 40 somatic mutations, including 10 mutations in genes recorded in the cancer gene list (Table EV1); primarily, we observed recurrent Notch1 (SNVs 5/10, indels 5/10) and KRas (SNVs 1/10) mutations, consistent with Rosa26‐Lmo2 + Sca1‐Cre and human LMO2+ T‐ALL pathogenesis." (PMID 29880602, 2018). "Therefore, NOTCH1 represents a new key cancer gene in CLL whose genetic and pathway alterations are likely to represent a novel oncogenic process in this disease." (PMID 29998084, 2018). "Many reports have shown that the overexpression of NOTCH1 could inhibit cell apoptosis in many cancers, which suggests its importance." (PMID 30072869, 2018). "Furthermore, based on the Pearson correlation analysis of TCGA Pan-Cancer, Notch1 expression was positively correlated with RELA (NF-κB(p65)) expression in GBM." (PMID 29410396, 2018). "Notch1-dependent regulation of EGFR has been described in several types of cancers." (PMID 29321718, 2018). "Moreover, PlexinD1 expression correlates with Notch1 and Notch3 in different cancer types, and its role in metastatic tumor progression has been further demonstrated in colon cancer, melanoma, and ovarian cancer." (PMID 29462871, 2018). "Importantly, because MDA-MB-231 LM and parental cells showed nominal levels of NOTCH1 and NOTCH2, these results suggest that LY411575-mediated inhibition of cancer cell seeding and metastatic growth was likely associated with NOTCH3 targeting." (PMID 30180881, 2018). "The Notch1 and Snail1 genes are important for cancer cell growth and invasion." (PMID 28145431, 2017).
cancer (continued). "Nethertheless, the enzymatic activity of γ-secretase in Notch1 signaling pathway and the mechanism of how γ-secretase inhibitor works on cancer cell are still unknown." (PMID 28030808, 2017). "This feed-forward circuit with DLL4, Notch3, MSI-1, NUMB and Notch1 may be relevant for the regulation of Notch during cancer formation." (PMID 29104587, 2017). "Finally, given the importance of NOTCH1 as an oncogene in other cancers, it is likely that similar effects on self-renewal, stemness, and cell-state transitions will be observed in other Notch-driven tumors." (PMID 28614716, 2017). "We also determined whether rottlerin impacted Notch-1 signaling pathway, leading to its anti-cancer properties." (PMID 28977931, 2017). "Notch-1 has been demonstrated to play an important role in regulating cancer stem cells, suggesting that fucose-bound liposomes could also target these cells." (PMID 27233074, 2016). "Therefore, preventing the generation of Notch1-IC is a potential strategy for treating various cancers." (PMID 27806347, 2016). "Other cancer-associated genes in Cluster B include ZEB2, NOTCH1, and FAT1." (PMID 26939613, 2016). "Therefore, activation of Notch1 (production of NICD) has been implicated in tumorigenesis, proliferation, and survival of several cancer cells." (PMID 26716415, 2016). "Both Pim kinases and Notch1 have been shown to promote cancer cell migration and invasion." (PMID 27281612, 2016). "We observed different expression of Notch1 and HO-1 in stroma and cancer; it is likely that CO targets similar receptors, namely mitochondrial hemeproteins, however downstream pathways may differ in these two cell types." (PMID 26993595, 2016). "Based on the oncogenic role of NOTCH1 in cancer development and progression, we hypothesized that NOTCH1 is likely regulated by EZH2." (PMID 27049834, 2016). "HO-1 and Notch1 are expressed in stroma cells as well as in cancer cells." (PMID 26993595, 2016). "We speculate that the mechanism of CO-induced Notch1 activation is likely through increased mitochondrial ROS in macrophages or cancer cells." (PMID 26993595, 2016). "Our strategy to target cancer cells, which actively take up L-fucose to produce fucosylated proteins such as sialylated antigens and growth factors in response to Notch-1 activation, can be utilized for killing Notch-1-expressing cancer cells in the same manner." (PMID 27233074, 2016). "Up-regulated expression of DLK1/Notch1 has been detected in various human cancers." (PMID 27455311, 2016). "To examine whether lentiviral vector-mediated knockdown of Notch-1 impacted on the proliferation of cancer cells, we examined the growth of lentivirally infected ACC-M cells by MTT assays." (PMID 25990317, 2015). "Because our study suggests a regulatory relationship between DLK1 and NOTCH1, it is natural to hypothesize that the abnormal expression of NOTCH1 in cancers is partially the consequence of aberrant expression of DLK1." (PMID 24621612, 2014). "Recently, Notch1 protein expression has been shown to regulate stem cells and cancer stem cells." (PMID 24396472, 2014). "NOTCH1 inhibitors might therefore have potential therapeutic applications in treating SACC patients by inhibiting cancer cell growth and metastasis." (PMID 25149541, 2014). "Previous studies found that Notch1 modulates NF-κB activity in macrophages and cancer cells." (PMID 24810405, 2014). "Increase in cells expressing CSC markers and Notch1 signaling pathway in tumors exposed to CIS may explain recurrence of cancer in patients treated with carboplatin and paclitaxel." (PMID 25264898, 2014).
cancer (continued). "This controversy suggests, at least, that 1) function of Notch 1 in NSCLC is diversified in different cells and different cancer stages; 2) Notch1 expression should be considered while treating patients; 3) we urgently need to understand the role of Notch1 in NSCLC." (PMID 25372032, 2014). "Because cell detachment leads to transient Notch1 activation in cancer cell lines, routine cell culture could inadvertently and repeatedly initiate transient Notch1 signaling and alter these key cellular processes." (PMID 25147757, 2014). "However, when IHC was used to gauge NOTCH1 activation in other human cancers, several unexpected findings emerged." (PMID 23825651, 2013). "In addition, the assay is specific for NOTCH1, and therefore cannot be used to assess activation of other NOTCH receptors, which have been implicated in certain cancers." (PMID 23825651, 2013). "In conclusion, the results of this study showed that the expression level of Notch1 may be gradually increased from precancerous lesions to cancer." (PMID 24312514, 2013). "Recently, Notch-1 was widely studied and reported to aberrantly express in malignant tumors." (PMID 24423157, 2013). "Although Notch1 signalling may play key roles in the maintenance of cancer stem cells, the druggable targets in Notch1 signalling are limited." (PMID 23651443, 2013). "Expression level of Notch1 was gradually increased from precancerous lesions to cancer." (PMID 24312514, 2013). "There is also evidence that NOTCH1 has important functional roles in endothelium and other stromal components that may contribute to the malignant behavior of cancers." (PMID 23825651, 2013). "In this article, our main objective was to find out the effects of those cross talking molecules, such as RAS, TWIST, ERK12, NOTCH1 or the loss of functions of few tumor suppressor proteins such as SUFU, GAS1, SUFU, NUMB, SNO in the three types of cancer scenarios discussed earlier." (PMID 23935937, 2013). "Thus, we report that CK2 participates in cancer stem cell maintenance by regulating Notch1 signalling." (PMID 23651443, 2013). "Numerous studies have demonstrated that the cancer stem cell phenotype is heterogeneous with one study showing at least two distinct populations with cancer stem cell characteristics and Notch1 expression in cell lines derived from a Brca1 knockout mouse model." (PMID 23863842, 2013). "Notch1 represents the first link of the Notch cascade to human cancer." (PMID 24312514, 2013). "NOTCH receptors (NOTCH1-4) are key positive regulators of cell-cell interactions, angiogenesis, cell adhesion and stem cell niche development which have been shown to play critical roles in several human cancers." (PMID 24143218, 2013). "In addition, it has been demonstrated that the downregulation of Notch-1 contributes to cell growth inhibition in various cancers." (PMID 23710217, 2013). "Furthermore, it is well studied that HDAC inhibitors, for example VPA, SBHA and TSA increased Notch1 at transcript and protein level in many cancers." (PMID 22583596, 2012). "Therefore, our findings have a potential impact on understanding the mechanism by which Notch-1 and c-Src signaling pathways regulate carcinogenesis and cancer cell growth." (PMID 22479394, 2012). "However, our observations are consistent with other studies which have shown that TSA treatment increases BMP2 mRNA level in human osteoclasts and also up-regulates Notch1 expression in cancer cells resulting in growth suppression." (PMID 22022609, 2011).